U6 (U6 spliceosomal RNA )
Synonyms: LOC124905169
Gene: Small nuclear RNA gene on chromosome 22 (16,141,767 to 16,141,872, forward strand). Ensembl gene ENSG00000278188.
Gene Ontology:
Molecular function: U4 snRNA binding
Biological process: formation of quadruple SL/U4/U5/U6 snRNP; spliceosomal tri-snRNP complex assembly
Cellular component: U4/U6 x U5 tri-snRNP complex; U6 snRNP
Homologues: Orthologues: macaque U6 (92% identical), dog U6 (65% identical), rabbit U6 (64% identical), pig U6 (61% identical), rabbit U6 (59% identical). Paralogues in human: RNU6-458P (99% identical), U6 (99% identical), RNU6-1293P (98% identical), RNU6-156P (98% identical), RNU6-1132P (96% identical), RNU6-614P (96% identical), RNU6-721P (95% identical), U6 (95% identical), RNU6-978P (94% identical), RNU6-1207P (92% identical), RNU6-811P (92% identical), RNU6-452P (88% identical), and 1289 more.